DDX3Y (DEAD-box helicase 3 Y-linked)
Diseases named in the same sentence as DDX3Y in open-access papers:
DDX3Y is named in the same sentence as 37 diseases in open-access papers, as found by Europe PMC text mining. Sharing a sentence is not in itself a finding about the gene and the disease. The quoted sentences say what the papers report.
Infertility (9 papers, 2012 to 2025). "Here we present four different likely pathogenic loss-of-function variants in the AZFa gene DDX3Y identified by analysing exome sequencing data of more than 1,600 infertile men." (PMID 36997603, 2023). "Expression of DDX3Y alone has been shown to rescue the specific infertility phenotype caused by deletion of AZFa, although these findings have been disputed in mice." (PMID 34535544, 2021). "Conversely, the loss of DDX3Y confers infertility in human males, despite the robust expression of DDX3X in germ-line tissues." (PMID 34535544, 2021). "The absence of DDX3X protein in premeiotic spermatids could explain its inability to rescue the infertility phenotype conferred by DDX3Y loss." (PMID 34535544, 2021). "Infertility patients with loss-of-function mutations in the DDX3Y gene presented the SCO phenotype, suggesting that DDX3Y is essential for spermatogenesis and male fertility." (PMID 39551844, 2024). "In the AZFa region, it has been suggested that Ddx3y is the main gene responsible for infertility." (PMID 38961864, 2024). "De novo deletions of the entire DDX3Y gene (so-called AZFa deletions) cause spermatogenic failure and, thereby, infertility but otherwise have no reported impact on somatic development, function, or health." (PMID 39026797, 2024). "Deletion of Ddx3y disrupts germ cell development and leads to infertility in males." (PMID 38961864, 2024). "The identification of infertile men with LoF variants in DDX3Y, therefore, further supports the assumption that activity of DDX3Y can also not be rescued in vivo by DDX3X, which is again a result of the celltype-specific expression profile of both proteins in testicular tissue." (PMID 36997603, 2023). "The ratio of infertility genes expression: DDX5, TNP2, DDX3Y, TDRD6, SOHL2, DDX31, and SYCP3 in infertility cell (azoospermia) in comparison to a normal cell." (PMID 36241908, 2022). "STRING and Cytoscape analyses presented seven genes, i.e., DDX5, TNP2, DDX3Y, TDRD6, SOHL2, DDX31, and SYCP3, as the hub genes involved in infertility with VASA co-function and protein–protein interaction." (PMID 36241908, 2022).
Azoospermia (6 papers, 2010 to 2024). Absence of any measurable level of sperm,whereby spermatozoa cannot be observed even after centrifugation of the semen pellet. "More recently, DDX3Y was identified as the critical spermatogenic factor in AZFa deletion-induced azoospermia." (PMID 39551844, 2024). "On the other hand, the human DDX3Y lies within the azoospermia factor a (AZFa) region on the proximal Yq11.21 and the deletion of human DDX3Y resulted in the oligozoospermia, azoospermia and the male sertoli-cell only syndrome." (PMID 20438638, 2010). "Analysing genetic data from 1,655 men with non-obstructive azoospermia (NOA) reveals four independent loss-of-function variants in DDX3Y, suggesting that it is a key gene in the AZFa region and should be considered in diagnostic workflows for NOA." (PMID 36997603, 2023). "Finally, the DDX3Y gene, along with KDM5D and EIF1AY, are azoospermia factors (AZFa)." (PMID 31817322, 2019).
male infertility (5 papers, 2019 to 2024). The inability of the male to effect fertilization of an ovum after a specified period of unprotected intercourse. "DDX3Y is expressed in spermatocytes, and loss of DDX3Y results in a male infertility phenotype despite robust DDX3X expression in male germline cells." (PMID 39444378, 2024). "Heterozygous genetic lesions in DDX3X mediate a class of developmental disorders called DDX3X syndrome, while loss of DDX3Y is implicated in male infertility." (PMID 34535544, 2021). "Foresta and coworkers suggested that DBY/DDX3Y might be an AZFa candidate because it is frequently deleted in male infertility, and its mutation significantly reduces or even abolishes the germ cell population." (PMID 31171972, 2019). "There are also male infertility cases caused by defects in single genes including CFTR, DDX3Y, SYCP3, TEX11, AURKC, and DPY19L2, but the number of genes confidently linked to male infertility remains very low." (PMID 34190021, 2022).
heart failure (4 papers, 2018 to 2023). Inability of the heart to pump blood at an adequate rate to meet tissue metabolic requirements. "An expression profiling study based on new-onset heart failures caused by idiopathic dilated cardiomyopathy demonstrated that USP9Y, DDX3Y, RPS4Y1, and EIF1AY were significantly upregulated in male patients with high-fold changes." (PMID 29361784, 2018). "In addition, an expression profiling study based on new-onset heart failures demonstrated that DDX3Y, EIF1AY, and USP9Y are upregulated in male subjects." (PMID 36831031, 2023). "In accordance with adjusted p < 0.05 and |fold-change|>1.5, five RBPs (EIF1AY, RPS4Y1, DDX3Y, RNASE2, and CSDC2) were found in heart failure LV myocardium specimens in comparison to nonfailing controls." (PMID 36313471, 2022).
lymphoma (4 papers, 2023 to 2025). A malignant (clonal) proliferation of B- lymphocytes or T- lymphocytes which involves the lymph nodes, bone marrow and/or extranodal sites. "Due to its very restricted expression, targeting DDX3Y in lymphoma patients harboring an activated c-MYC allele in addition to a DDX3X LOF is very likely the best strategy." (PMID 37035206, 2023). "However, patients with a loss of DDX3Y – i.e male patients whose cancer cells have lost their Y chromosome – carry lymphoma cells relying only on the DDX3X paralog." (PMID 37035206, 2023). "For example, male lymphomas rely on functional compensation by DDX3Y for rescue, and inhibitors blocking DDX3Y can eliminate cancerous B cells." (PMID 37350942, 2023). "Conversely, in lymphoma patients harboring a DDX3X mutation, selective inhibition of DDX3Y without affecting DDX3X would be extremely advantageous as it would target only lymphoma cells relying on DDX3Y." (PMID 37035206, 2023). "It would be only once a lymphoma is established that aberrant expression of DDX3Y can be induced in malignant B cells to restore full translation capacity and to adopt a level of protein synthesis required for tumor development." (PMID 37035206, 2023). "Loss of DDX3X function prevents MYC oncogene-driven lymphomagenesis by moderating global protein synthesis and buffering MYC-induced proteotoxic stress, but established male lymphoma cells can overcome this effect by aberrantly upregulating DDX3Y protein levels." (PMID 39975375, 2025). "Since these patients are almost exclusively males, and their lymphoma cells rely on the aberrant expression of the DDX3Y protein, DDX3 inhibitors could be beneficial for eliminating cancer cells." (PMID 37035206, 2023). "Human DDX3Y was detected in leukemia and lymphoma cells, but undetected in normal B lymphocytes." (PMID 37035206, 2023). "In B cell lymphomagenesis, DDX3Y protein is detected only in established male lymphoma cells but not in normal male B cells." (PMID 39975375, 2025). "DDX3 being an essential gene, at least one of the two paralogs is indispensable for cell survival, particularly in a B cell lymphoma context as shown by the aberrant DDX3Y expression in human lymphoma with a DDX3X LOF; and by the DDX3Y overexpression in murine lymphoma cells with a Ddx3x KO." (PMID 37035206, 2023).
Sertoli Cell-Only Syndrome (3 papers, 2018 to 2025). A type of male infertility in which no germ cells are visible in any of the biopsied SEMINIFEROUS TUBULES (type I) or in which germ cells are present in a minority of tubules (type II). "Although human individuals carrying mutations or deletions of the DDX3Y gene have not been reported, knockout of the DDX3Y gene can also cause reproductive disorders, namely, sertoli cell only syndrome (SCOS), which is characterized by no germ cells in the testis, a low testis volume, and high FSH." (PMID 35912115, 2022). "Secondly, three IR-rich genes (USP9Y, DDX3Y, DAZ1), or their protein products, play a significant role in Sertoli cell-only syndrome (DOID:0050457)." (PMID 41155472, 2025).
Alzheimer disease (2 papers, 2022 to 2024). A progressive, neurodegenerative disease characterized by loss of function and death of nerve cells in several areas of the brain leading to loss of cognitive function such as memory and language. "In the brain, Alzheimer’s disease and memory-related genes (Camk2n1, Apod, and Serpina3n), and immune-response-related genes (Spp1, CD68, GFAP, Mpeg, Ddx3y, Lyz2, CTSZ, Tyrobp, C4b, and C1qa), were selected for mRNA qPCR analysis in adenine-induced CKD mice." (PMID 35447931, 2022).
colorectal cancer (2 papers, 2021 to 2022). A primary or metastatic malignant neoplasm that affects the colon or rectum. "In order to dissect the similarities and differences between the functions of DDX3X and DDX3Y, we used a cell line we generated to rapidly and efficiently degrade endogenous DDX3 protein X in human male-derived colorectal cancer HCT 116 cells, which show a stable diploid karyotype." (PMID 34535544, 2021).
lung carcinoma (2 papers, 2022 to 2025). "Out of 12 hub genes, only 4 (IRAK2, SREK1, C1QTNF2 and DDX3Y) have shown significant gene expression in lung cancer compared to the normal tissues." (PMID 36194576, 2022). "Recent work has also found that DDX3Y is stabilized by USP9Y, and tumor suppressive effects were observed in lung cancer cells when both DDX3Y and USP9Y were overexpressed." (PMID 40454088, 2025).
atherosclerosis (1 paper, 2023). A disease characterized by the build-up of fatty material and calcium deposition in the arterial wall resulting in partial or complete occlusion of the arterial lumen. "The present study identifies genes already classified in the atherosclerosis process as genes that codify for encoding cellular adhesion molecules (NLGN4Y), cellular exocytosis (TXLNGY), induction of IFN-α (DDX3Y), cellular apoptosis (EF1AY), and prevention of protein degradation (USP9Y)." (PMID 36831031, 2023).
B cell lymphomas (1 paper, 2023). "The recent discovery of the aberrant expression of DDX3Y compensating the loss of DDX3X function in tumors with c-MYC activation has opened a new area for developing new therapeutic strategies for B cell lymphomas." (PMID 37035206, 2023). "However, one observation that remained coherent between the two studies is that both models, male BL patients and male mice with immature B cell lymphoma, show respectively aberrant and high DDX3Y expression that compensates for the loss of DDX3X." (PMID 37035206, 2023). "Moreover, given that a pharmacological inhibition of c-MYC is difficult, inhibition of DDX3X or DDX3Y could represent alternative therapeutic avenues for the treatment B-cell lymphoma in male patients with DDX3X LOF mutations." (PMID 37035206, 2023). "In this case, specific DDX3Y inhibitors blocking its enzymatic activity or any other strategy abolishing DDX3Y protein would eliminate the B-cell lymphoma, but not other cells, since DDX3Y is not expressed in most normal cells." (PMID 37035206, 2023).
Burkitt lymphoma (1 paper, 2023). A rare form of malignant mature B-cell non-Hodgkin lymphoma. "As sex chromosome‐specific genes, the functional difference between DDX3X and DDX3Y might explain the gender differences in the incidence rate of Burkitt lymphoma." (PMID 36971051, 2023).
colon cancer (1 paper, 2025). "In HCT116 colon cancer cells, we detected 44% increase in endogenous DDX3Y following siRNA-mediated knockdown of DDX3X." (PMID 39975375, 2025).
Constipation (1 paper, 2024). Infrequent or difficult evacuation of feces. "The present results suggest that C3 deficiency-induced constipation may be associated with 1237 upregulated genes including PNLIP, CEL, CPB1, CTRL, PNLIPRP1, and REG1 as well as 1292 downregulated genes including Eif2s3y, UTY, KDM5D, IGKV6-32, Olfr870, and DDX3Y." (PMID 39273477, 2024).
COVID-19 (1 paper, 2023). A disease caused by infection with severe acute respiratory syndrome coronavirus 2. "Examination of the top DEGs enriched and depleted in male versus female COVID-19 Mo/DCs revealed appropriate recovery of Y-linked genes (DDX3Y, EIF1AY, and UTY) and XIST, which enables X chromosome inactivation and, thus, is increased in female cells." (PMID 37606044, 2023).
epilepsy (1 paper, 2025). A brain disorder characterized by episodes of abnormally increased neuronal discharge resulting in transient episodes of sensory or motor neurological dysfunction, or psychic dysfunction. "Neither treatment prior to surgery(chemotherapy, radiotherapy, steroids) nor confounding factors (age,epilepsy) were significantly associated with any of the DEPs, althoughsex impacted the expression of Y-chromosome-encoded adenosine triphosphate(ATP)-dependent RNA helicase DDX3Y (DDX3Y)." (PMID 40518661, 2025).
glaucoma (1 paper, 2023). Increased pressure in the eyeball due to obstruction of the outflow of aqueous humor. "Database analysis revealed that seven host genes (NEAT1, SAMD12, KDM5D, ZFY, EIF1AY, TXLNGY, and DDX3Y) of nine DEcircRNAs were also differentially expressed in blood samples of patients with glaucoma, and the trend of differential expression of circRNAs and host genes was consistent." (PMID 37805546, 2023).
megacolon (1 paper, 2020). "The exact molecular mechanism by which DDX3Y may contribute to the development of aganglionic megacolon in a sensitized genetic background is currently unknown." (PMID 32898154, 2020). "Considering that the vast majority of HSCR patients display aganglionosis over only a short segment of the distal colon, such intervention might well be sufficient to prevent megacolon occurrence in many male individuals (up to 50% of them according to our human DDX3Y immunofluorescence data)." (PMID 32898154, 2020).
oral cancer (1 paper, 2022). "This study demonstrated the pro-tumor roles of CCL13 in oral cancer and illustrated that stress granules appeared to a positive regulator of CCL13 expression in M2 TAMs via improving the DDX3Y/hnRNPF-mediated mRNA stability of CCL13." (PMID 36291863, 2022).
spermatogenic failure (1 paper, 2023). A male infertility characterized by dirsuption of the process of sperm development from diploid cells into mature haploid spermatozoa. "By describing four different LoF variants in DDX3Y in azoospermic men, this study provides sufficient evidence that DDX3Y is the key gene leading to spermatogenic failure observed in men with complete AZFa deletions." (PMID 36997603, 2023).
viral infection (1 paper, 2017). "As for DDX58, NFκB1, TOLLIP, RIPK1, DDX3Y, TRIM25 and JAK2, which are involved in antiviral signalling transduction, both increased mRNA abundance and switched poly(A) sites eventually led to enhanced protein production following viral infection." (PMID 28233779, 2017).
cancer (12 papers, 2016 to 2026). A tumor composed of atypical neoplastic, often pleomorphic cells that invade other tissues. "Genome sequencing has identified numerous mutations in the DEAD‐box RNA helicases, DDX3X and DDX3Y, associated with cancer and other diseases, but monitoring of their functional consequences remains a challenge." (PMID 40385543, 2025). "Here, we investigated the regulation of DDX3Y by DDX3X in two male-derived human cancer cell lines, HCT116 and U87MG." (PMID 39975375, 2025). "RPS4Y1 and DDX3Y have been among downregulated genes in 12 cancers in a recent whole transcriptome analysis." (PMID 36119500, 2022). "DDX3Y is especially important for spermatogenesis and male fertility, but also dual correlation of DDX3Y with cancer patient survival in different cancer types has been described." (PMID 33974127, 2021). "Here, we found nonsynonymous variants impacting AMELY, DDX3Y, RPS4Y2, and TBL1Y in five African tumors (4.7%), and UTY in a single European tumor (1.8%), highlighting the potential for these chrY genes as ancestry-specific cancer driver candidates." (PMID 40454088, 2025). "As an alternative to targeting DDX3Y enzymatic activity, a direct or indirect elimination of the DDX3Y protein may be sufficient to eliminate cancer cells." (PMID 37035206, 2023). "There was a very high-degree of commonality across all the models, with three Y-chromosome genes selected across all 17 cancers (ZFY, EIF1AY, and DDX3Y), RPS4Y1 (also on the Y-chromosome) selected across 15 of 17 cancers, and XIST (on the X-chromosome) selected across 14 of 17 cancers." (PMID 26755347, 2016). "Since DDX3Y is not expressed in normal human cells, these data suggest that DDX3Y may represent a new cancer cell specific target to develop adjuvant therapies for male patients with BL and DLBCL and LOF mutations in the DDX3X gene." (PMID 37035206, 2023).
tumor (11 papers, 2016 to 2025). "Nonsynonymous mutations were found in the genes AMELY, DDX3Y, RPS4Y2, TBL1Y in African tumors (5 samples: 4 HRPCa 1 LRPCa), and in UTY in one European HRPCa tumor." (PMID 40454088, 2025). "Immunohistochemical analysis revealed significantly higher expression levels of EIF4G2, SEPBP1, and DDX3Y in tumor tissues." (PMID 38603733, 2024). "As in tumors, the genes ZFY, RPS4Y1, DDX3Y were selected in all of the tissue types for the male vs. tumor analyses in normal samples, and RPS4Y1 was selected in the majority of tissue types." (PMID 26755347, 2016). "Similarly, DDX3Y protein expression was significantly higher in tumor tissues than in normal ovarian tissues." (PMID 38603733, 2024). "The spatial transcriptome data identified differential expression of DDX3Y, PGR and NKX2‐2 between tumour samples and normal samples." (PMID 39548559, 2024). "It is thus likely that DDX3Y compensates the loss of DDX3X and suggests that DDX3 proteins are required for malignant transformation and are not tumor suppressors." (PMID 40772229, 2025). "The 22 common hub genes, except DDX3Y, SEP15, and EFEMP2, from both groups were also common in the hub of hub genes, with the mean degree of the common hub of hub genes being 4.8 (range, 2–10) in the normal and 4.27 (range, 2–12) in the tumor." (PMID 40457491, 2025). "Since the survival of Daudi cells depends on DDX3Y overexpression because DDX3X expression is undetectable, these results suggest RK-33 is also effective in blocking DDX3Y to slow down tumor progression and that inhibition of both DDX3 paralogues can contribute to tumor suppression." (PMID 40772229, 2025).
immune diseases (1 paper, 2014). "We thus presume that the upregulated DEGs such as Cav1, CD200R1, TNFRSF17 and CXCR3 and downregulated DEGs such as EIF1AY and DDX3Y in healthy female may be involved in gender predominance of some immune diseases." (PMID 24741625, 2014). "Moreover, the upregulated DEGs (Cav1, CD200R1, TNFRSF17, and CXCR3) and downregulated DEGs (EIF1AY and DDX3Y) in healthy female may be involved in gender predominance of some immune diseases." (PMID 24741625, 2014).
DDX3Y also shares sentences with these, for which no sentence is quoted: autism (2 papers); idiopathic dilated cardiomyopathy (2); asthma (1); dysgerminoma (1); gonadoblastoma (1); hepatocellular carcinoma (1); Intellectual disability (1); lung disease (1); major depressive disorder (1); medulloblastoma (1); mild cognitive impairment (1); prostate tumor (1); seminoma (1).